APC (APC regulator of Wnt signaling pathway)
Diseases named in the same sentence as APC in open-access papers (continued):
Sharing a sentence is not in itself a finding about the gene and the disease.
polyposis (continued). "Obviously, patients with de novo MMR mutations could be represented in our study, but a number of studies have indicated that Lynch de novo mutation are relatively rare compared to e.g., APC related polyposis and it is estimated that only 1–3% of all HNPCC cases are caused by MMR de novo mutations." (PMID 31263571, 2019). "Therefore, the high densities of mMCP5+ and mMCP6+ MCs in 5CreCAT mice had higher densities of both stromal and intraepithelial mMCP5+ MCs than age matched TS4Cre APClox468 (cAPC) mice that develop polyposis due to loss of function of APC in gut epithelial cells." (PMID 31849960, 2019). "Today, most genetic analyses are done with a next generation sequencing (NGS) panel comprising several polyposis-associated genes (including SMAD4 and APC)." (PMID 39039610, 2024). "In total, 379 unexplained polyposis patients were tested for somatic APC mosaicism using targeted NGS." (PMID 38238650, 2024). "The most common LPV (50/84 patients) was APC:c.3902T>A; all carriers were Ashkenazi Jewish or partly Ashkenazi Jewish, except for one Israeli Arab with polyposis." (PMID 38201524, 2023). "APC-associated polyposis also includes gastric adenocarcinoma and proximal polyposis of the stomach (GAPPS) caused by pathogenic variants in the promoter 1B of the APC." (PMID 34185173, 2021). "Variants at the 3′ and 5′ ends of the gene produce either a very small protein or a protein of almost normal length, allowing wild type APC to function almost normally and producing attenuated polyposis." (PMID 34680910, 2021). "In the past, deep-intronic and promoter variants were described in tumor suppressor genes APC and PTEN, which makes sequencing of these non-coding regions of particular interest for unresolved hCRC and polyposis patients." (PMID 33228212, 2020). "MSI1 binds to and negatively regulates translation of Numb and APC (adenomatous polyposis coli), negative regulators of Notch and Wnt signaling respectively." (PMID 30097032, 2018). "Equally interesting is the high age of polyposis diagnosis (58 years) in patients belonging to the APC AFAP group harbouring the wildtype genotype (GG) for SNP rs1761667." (PMID 30065793, 2018). "It is quite likely that, in the APC Min/+ model of polyposis, IL-33 promotes polyposis formation via Th2 cytokines IL-4 and IL-13 as well as inflammatory cytokine IL-6, which facilitate mast cell function." (PMID 29499051, 2018). "In 23 APC carriers, polyposis was diagnosed at a mean age of 32 years (range: 9–60 years) without CRC on endoscopic evaluation or histopathological examination of prophylactic procto-colectomy." (PMID 28533537, 2017). "Of the 60 APC mutation carriers, 31 had developed CRC at a mean age of 38.3 years (range years) in a background of classical polyposis with hundreds to thousands of polyps in all but one case of AFAP with only 50 polyps." (PMID 28533537, 2017). "In summary, our results support the concept that APC haplo-insufficiency of the host colonic epithelial cell alters colonic microbial interactions prior to polyposis." (PMID 26121046, 2015). "This first comprehensive investigation of the APC and MUTYH mutation spectrum in Brazilian polyposis patients showed a high detection rate and identified novel pathogenic mutations." (PMID 23561487, 2013). "Considering that this study is the first comprehensive analysis of APC and MUTYH mutations in Brazilian polyposis patients, we attempted to determine the most cost-effective approach to detect the causative mutation in this population." (PMID 23561487, 2013).
polyposis (continued). "The aim of this study was to conduct a comprehensive molecular analysis to determine the spectrum of point mutations and large genomic rearrangements (LGR) in the APC and MUTYH genes in a series of 23 Brazilian polyposis patients." (PMID 23561487, 2013). "Nowadays, the gold standard detection method for polyposis patients is direct DNA sequencing of all APC and MUTYH coding exons (including intron–exon boundaries), accompanied by screening for LGR, as was performed here." (PMID 23561487, 2013). "One case of use of aberrant splice-acceptor site of APC exon 8 has been reported previously in a patient with classical polyposis." (PMID 18433509, 2008). "Copy number loss was observed in two patients with polyposis who had no germline APC variants in any sample tissue." (PMID 41488735, 2025). "APC (NM_000038.5) c.1042C>T (p.Arg348Ter; GRCh37 chr5:112154771-C-T) has been identified in six probands over the age of 50 who did not report a clinical history of polyposis or other APC-associated phenotypes (OMIM #175100)." (PMID 41300834, 2025). "APC somatic (postzygotic) mosaicism was reported in up to 50% of unexplained adenomatous polyposis cases and is mainly detected in patients with an attenuated polyposis phenotype." (PMID 40237877, 2025). "Similarly to as in the absence of IBD, in the case of LS, the most prevalent mutation in the overlap population concerns MLH1, just as in the case of polyposis the most frequently defective gene is APC also in IBD-polyposis populations." (PMID 39272825, 2024). "A specific group of patients with polyposis and mental retardation may present with large (usually de novo) chromosomal deletions encompassing the 5q22 region which harbors the APC gene." (PMID 35158896, 2022). "CTNNB1 and APC mutations being exclusive, routine screening of polyposis is not a standard of care when the DT harbors CTNNB1 mutation." (PMID 35251801, 2022). "In this study, we investigated 80 unexplained colorectal polyposis patients without germline pathogenic variants in known polyposis predisposing genes to detect mosaic and deep intronic APC variants." (PMID 33683519, 2022). "We named these patients with polyposis without an identifiable APC pathogenic variant as APC negative polyposis." (PMID 33628596, 2021). "Some striking examples of the protective function of MCs in cancer include a recent study where the genetic ablation of ACKR2, a decoy chemokine receptor, in the Min-APC mouse model of polyposis increased recruitment of MCs and led to tumor rejection in a MC and CD8 dependent manner." (PMID 31849960, 2019). "One patient had a family history of maternal rectal cancer, although the cancer was not of polyposis type and was diagnosed at the age of 70 years, which can hardly be seen to be associated with APC gene mutation." (PMID 31269945, 2019). "In one family, with allelic variant c.3066insGA, one of the children was negative for allelic variant in APC, while the other was positive and colonoscopy was positive for polyposis in the rectum." (PMID 31547110, 2019). "Various studies did not detect large germ line APC deletions in attenuated polyposis patients; however, Pilarski, Brothman, Benn, & Shulman (1999) reported an attenuated polyposis case associated with the germ line deletion of the entire gene." (PMID 30259713, 2018). "We found, not APC mutation, but three other alteration pathways as likely reasons of this canine extreme polyposis." (PMID 30018743, 2018).
polyposis (continued). "We have previously identified a copy number variant (CNV) region that regulates PPM1L, a novel serine-threonine phosphatase, in APC-mutation negative familial CRC patients with aggressive polyposis via genome-wide scan." (PMID 28306719, 2017). "In this study, we embarked on the search of novel genes in one of the APC-mutation negative families with attenuated polyposis in which other possible tumour suppressors had been ruled out." (PMID 28306719, 2017). "It seems as if patients with mutations in APC, BMPR1A, SMAD4 and GREM1 can have similar polyposis phenotypes but carriers of GREM1 mutation with HMPS might not have the same risk for extra-colonic disease as patients with BMPR1A mutations and HMPS." (PMID 27696107, 2017). "ApcMin/+ mice have a mutation in the APC gene and accelerate polyposis in the intestine but not colon." (PMID 29041928, 2017). "The polyposis was not explained by a germline mutation in APC or MYH and all patients received abdominal radiotherapy." (PMID 27821077, 2016). "Bi-allelic pathogenic MUTYH variants are found in a quarter of polyposis patients negative for pathogenic APC variants." (PMID 25604157, 2015). "In parallel, HRM APC scanning was applied to DNA isolated from polyp tissue of two additional patients with apparently sporadic polyposis and without detectable pathogenic APC variant in leukocyte DNA." (PMID 25604157, 2015). "Both patients had a clear polyposis phenotype and early age of onset, without detectable pathogenic germ line variants in the APC gene or MUTYH gene." (PMID 25604157, 2015). "However, two considerations warrant further examination of the APC gene, with its paramount role in the mechanism of polyposis and somatic defects in almost all adenomatous polyps." (PMID 25604157, 2015). "Additionally, there were four cases in whom mutations in polyposis genes were detected (i.e. two MUTYH and two APC); yet these individuals had insufficient numbers of polyps to meet NCCN testing criteria for polyposis syndromes." (PMID 24506336, 2014). "The frequency of biallelic carriers of 2 most prevalent Caucasian mutations, p.Y179C and p.G396D, among APC negative patients with polyposis was 2-40%, and the frequency of carriers of monoallelic MUTYH mutations among CRC patients was 0.9-4.2%." (PMID 21901162, 2011). "Germline mutations in the MYH gene (autosomal recessive inheritance) have been shown to be present in the absence of germline mutations in the APC gene in patients with polyposis, and are discussed further below." (PMID 19424478, 2008). "Based on the publications to date, it can be concluded that APC mosaicism is a relevant, but still underreported cause of adenomatous polyposis, especially in cases with a more attenuated phenotype without a family history of polyposis." (PMID 40237877, 2025). "It is of note that one of these three carriers also had multiple adenomatous colonic polyps, raising the suspicion of APC-associated polyposis; however, neither him, nor the other two patients with desmoids, were found to carry a disease-causing variant in APC or in other polyposis-related genes." (PMID 38540414, 2024). "Furthermore, while APC mutations in FAP lead to a severe polyposis largely restricted to the colon, Apc mouse models are not fully reflective of human disease and lead to tumors located primarily within the small intestine." (PMID 35999641, 2022). "Therefore, we conducted a multi-center clinical study of the Chinese population to collect pedigrees of APC negative polyposis, aiming to find a novel disease-causing gene for adenomatous polyposis." (PMID 33628596, 2021). "Furthermore, this report highlights the need to develop dedicated surveillance guidelines for children with APC-related polyposis and raise the question whether to suspect and screen for APC-related conditions in cases of sporadic hepatoblastomas." (PMID 33588901, 2021).
polyposis (continued). "After the identification of APC, the phenotype expanded to include variant forms of the disease, which ranged from very mild disease (reduced expressivity) to allelic variants that did not display overt polyposis." (PMID 33926505, 2021). "Our case illustrates that a history of extra-abdominal fibromatosis may be an indication for colonoscopy and APC genetic testing, and that APC mosaicism may be the cause of not just single cases of polyposis but also of the extra-colonic features of FAP." (PMID 29368261, 2018). "Because mutation of porcine APC is sufficient to initiate polyposis without any further engineered mutation, spontaneous events that drive the transition from polyps to cancer can be investigated over time by colonoscopic monitoring and biopsy using standard human equipment." (PMID 29419487, 2018). "DNA sequencing of the complete coding region of the APC and MUTYH genes was performed in 23 unrelated Brazilian polyposis patients." (PMID 23561487, 2013). "Based on our findings, we recommend including APC and MUTYH in LS syndrome gene panels, as many patients harbor pathogenic variants in these genes despite lacking the typical polyposis phenotype." (PMID 40823072, 2025). "Our ultimate goal is to enable an appropriate approach to prophylactic strategies in Polish families with polyposis, especially in those patients whose APC, MUTYH, STK11, BMPR1A, and SMAD4 gene testing showed no abnormalities." (PMID 37834005, 2023). "Adenomatous polyposis coli (APC) negative polyposis patients were identified through next-generation sequencing and multiplex ligation-dependent probe amplification." (PMID 33628596, 2021). "The clinical characteristics, including the age at first visit, sex, FAP classification, extra-intestinal manifestation, and the family history of patients with APC negative and APC mutant polyposis are summarized in SupplementaryTable S4." (PMID 33628596, 2021). "Among all the non-MMR genes, APC, MUTYH and SMAD4 are well known to be implicated in CRC, specifically in polyposis." (PMID 30256826, 2018). "In the same vein, another study shows that ST2 deficiency does not affect polyposis in large intestine but does reduce polyposis in small intestine in the APC Min/+ model." (PMID 29499051, 2018). "No alterations in APC or MUTYH genes were present in the polyposis group, and alterations in MUTYH or the MMR genes/proteins and tumor microsatellite instability were absent in the early-onset CRC group." (PMID 28423643, 2017). "To model human CRC, we used TS4Cre × APClox468 mice that develop polyps in the colon and distal ileum, unlike the APC Min mice that exhibit polyposis mainly within the small intestine." (PMID 27918452, 2016). "In this study, we examined the mutational spectrum of the APC gene in patients with polyposis from two Spanish populations, and also the contribution of MUTYH germline mutations in those APC-negative patients." (PMID 19531215, 2009). "Twenty-four percent of the APC-negative patients carried biallelic MUTYH germline mutations, and showed an attenuated polyposis phenotype generally without extracolonic manifestations." (PMID 19531215, 2009). "Consistent with our expectations, patients with APC negative polyposis were diagnosed at a later age, and had a lighter polyp load, with fewer extra-intestinal manifestations and a family history related to polyposis." (PMID 33628596, 2021). "Patients with multiple polyps presented 10–100 polyps, being the main precursor lesion adenomatous, serrated or a combination of adenomatous and serrated polyps with an age of onset < 70 and no alterations in the APC or MUTYH genes." (PMID 28423643, 2017). "Finally, our patient series includes 17 families with no germline APC or MUTYH mutation detected, although ten of them belong to the classical FAP group with profuse polyposis." (PMID 26446593, 2016).
polyposis (continued). "In up to 50 % of polyposis families no germline mutation is identified and about 10–15 % of FAP patients could have a reduced APC expression with similar phenotype to patients with truncating APC mutation." (PMID 26511139, 2015). "The remaining eight patients presented an attenuated polyposis burden (< 100 polyps), among whom five carried biallelic mutations in the MUTYH gene, one carried a novel APC duplication of exons 1–3, one presented a novel APC missense variant, and one was mutation-negative." (PMID 23561487, 2013). "Unlike APC and MUTYH polyposis, POLD1/POLE syndrome is characterized by the development of extraintestinal tumors, including endometrial, ovarian, brain, and pancreatic cancers." (PMID 39661238, 2025).